MLYCD (malonyl-CoA decarboxylase)
Description:
Catalyzes the conversion of malonyl-CoA to acetyl-CoA. In the fatty acid biosynthesis MCD selectively removes malonyl-CoA and thus assures that methyl-malonyl-CoA is the only chain elongating substrate for fatty acid synthase and that fatty acids with multiple methyl side chains are produced. In peroxisomes it may be involved in degrading intraperoxisomal malonyl-CoA, which is generated by the peroxisomal beta-oxidation of odd chain-length dicarboxylic fatty acids. Plays a role in the metabolic balance between glucose and lipid oxidation in muscle independent of alterations in insulin signaling. May play a role in controlling the extent of ischemic injury by promoting glucose oxidation.
Synonyms: MCD; hMCD
Tractability: Small molecule: a structure with a bound ligand is known; a high-quality ligand is known; it belongs to a druggable protein family. PROTAC: its protein half-life has been measured; a small molecule that binds it is known.
Target class: Enzyme; Lyase
Gene: Protein-coding gene on chromosome 16 (83,899,115 to 83,951,445, forward strand). Ensembl gene ENSG00000103150.
Subcellular location: Cytoplasm; Mitochondrion matrix; Peroxisome; Peroxisome matrix
Pathways (Reactome):
Metabolism: Beta-oxidation of very long chain fatty acids
Protein localization: Peroxisomal protein import
Gene Ontology:
Molecular function: identical protein binding; malonyl-CoA decarboxylase activity
Biological process: acetyl-CoA biosynthetic process; fatty acid biosynthetic process; malonyl-CoA catabolic process; positive regulation of fatty acid oxidation; regulation of glucose metabolic process; acyl-CoA metabolic process; response to ischemia; fatty acid oxidation; regulation of fatty acid beta-oxidation; regulation of fatty acid oxidation; response to nutrient
Cellular component: cytoplasm; mitochondrial matrix; mitochondrion; peroxisome; cytosol; peroxisomal matrix
Genetic constraint (gnomAD): Loss-of-function variants: 33 observed, 37.87 expected, observed/expected ratio (o/e) 0.87, 90% interval 0.66 to 1.16. The synonymous counts are far from expectation, so gnomAD's model fits this gene poorly and the ratio says little. Missense variants: 839 observed, 573.51 expected, observed/expected ratio (o/e) 1.46, 90% interval 1.38 to 1.55. Synonymous variants: 360 observed, 254.83 expected, observed/expected ratio (o/e) 1.41, 90% interval 1.29 to 1.54.
Gene-disease validity (ClinGen):
ClinGen rates the evidence that MLYCD causes each of these diseases.
malonic aciduria (autosomal recessive): Definitive. Malonic aciduria is a metabolic disorder caused by deficiency of malonyl-CoA decarboxylase (MCD).
Homologues: Orthologues: chimpanzee MLYCD (99% identical), dog MLYCD (88% identical), rat Mlycd (88% identical), mouse Mlycd (88% identical), guinea pig MLYCD (87% identical), pig MLYCD (85% identical), tropical clawed frog mlycd (66% identical), zebrafish mlycd (58% identical), Caenorhabditis elegans mlcd-1 (33% identical).
Diseases named in the same sentence as MLYCD in open-access papers:
MLYCD is named in the same sentence as 31 diseases in open-access papers, as found by Europe PMC text mining. Sharing a sentence is not in itself a finding about the gene and the disease. The quoted sentences say what the papers report.
Malonic acidemia (3 papers, 2020 to 2023). "Malonic aciduria is an extremely rare inborn error of metabolism due to malonyl-CoA decarboxylase deficiency." (PMID 34884438, 2021). "Malonic acidemia (MA) is a cerebral OA occurring as a result of malonyl-CoA decarboxylase (MCD) deficiency and is caused by pathogenic variants in MLYCD." (PMID 33415129, 2020). "Malonic aciduria is an extremely rare inborn error of metabolism due to malonyl-CoA decarboxylase (MCD—EC." (PMID 34884438, 2021).
Obesity (3 papers, 2014 to 2025). Accumulation of substantial excess body fat. "In a murine model of HFpEF induced by obesity and hypertension, the expression of malonyl-CoA decarboxylase (MCD), an indirect regulator of fatty acid metabolism, was significantly upregulated." (PMID 41425991, 2025). "Many of the proteins identified in the present study that showed increased expression with obesity are predominantly involved in energy utilization, either fatty acid β oxidation (e.g. malonyl-CoA decarboxylase (MLYCD)) or glucose oxidation (e.g. pyruvate dehydrogenase kinase isozyme 4 (PDK4))." (PMID 30061171, 2018).
pulmonary hypertension (2 papers, 2016 to 2021). Increased pressure within the pulmonary circulation due to lung or heart disorder. "Fatty acid oxidation and malonyl CoA decarboxylase play critical roles in the metabolic processes involved in pulmonary hypertension." (PMID 34185184, 2021).
Sepsis (2 papers, 2025). Sepsis is defined as life-threatening organ dysfunction caused by a dysregulated host response to infection. "Expression of the flux-controlling enzyme of fatty acid synthesis, acetyl-CoA-carboxylase A (Acaca), was upregulated, whereas gene expression of malonyl-CoA-decarboxylase (Mlycd) was downregulated in prolonged sepsis." (PMID 39821755, 2025). "Targeting this pathway, for example, by enhancing SIRT5 activity to eliminate malonyl-CoA decarboxylase or by supplying malonyl-CoA decarboxylase to consume malonyl-CoA, could be a therapeutic strategy to protect the heart (and possibly other organs) in sepsis." (PMID 41107644, 2025).
cardiac ischemia (1 paper, 2013). "In fact, malonyl-CoA decarboxylase knockout (MCD-/-) mice that exhibit diminished cardiac β-oxidation do not undergo diet-induced loss of cardiac insulin sensitivity and glucose utilization and are protected from cardiac ischemia and reperfusion injury." (PMID 24116221, 2013).
cardiomyopathy (1 paper, 2017). A disease of the heart muscle or myocardium proper. "The disturbance of propanoate metabolism (deficiency of methylmalonyl-CoA mutase, propionyl-CoA carboxylase and malonyl-CoA decarboxylase) can cause many metabolic diseases characterized by developmental delay, seizure, hypoglycemia, cardiomyopathy and malonic aciduria." (PMID 28808302, 2017).
diabetes (1 paper, 2021). "Cardiac malonyl CoA levels are decreased in diabetes as a result of a decrease in its synthesis by acetyl-CoA carboxylase (ACC) and/or an increased degradation by malonyl CoA decarboxylase (MCD)." (PMID 34831481, 2021).
gliosarcoma (1 paper, 2019). A rare histological variant of glioblastoma (WHO grade IV) characterized by a biphasic tissue pattern with alternating areas displaying glial and mesenchymal differentiation (WHO). "Several mRNAs: MLYCD, CFAP54, ATP9B, and TMEM212 were significantly downregulated in gliosarcomas when compared to GBMs." (PMID 30818875, 2019).
hyperlipidemia (1 paper, 2022). "The PPARs-agonists (GW409544 and rosiglitazone) reduced hyperlipidemia via boosting malonyl-CoA decarboxylase protein production (MCD), which reduces the risk of myocardial infarction in patients with metabolic syndrome." (PMID 36422550, 2022).
infarction (1 paper, 2020). A localised pathological necrosis of tissue resulting from obstruction of the blood supply usually by a thrombus, an embolus, or vascular torsion. "Recently, an acute inhibition of malonyl-CoA decarboxylase (MCD) (potentiating the malonyl-CoA-dependent inhibition of FFA entry to the mitochondria) resulted in a switch from FFA to glucose utilization in normal rat hearts, and improved EF and SV in post-infarction failing hearts." (PMID 32824903, 2020).
Insulin resistance (1 paper, 2025). Increased resistance towards insulin, that is, diminished effectiveness of insulin in reducing blood glucose levels. "In support of this, in vitro overexpression of malonyl-CoA decarboxylase (MCD, an enzyme that depletes malonyl-CoA) in hepatocytes was shown to reduce malonyl-CoA levels and reverse insulin resistance, suggesting that lowering the malonylation potential can alleviate metabolic defects." (PMID 41107644, 2025).
osteosarcoma (1 paper, 2023). A usually aggressive malignant bone-forming mesenchymal neoplasm, predominantly affecting adolescents and young adults. "First, its expression was verified using the GEO dataset, and both GSE225588 and GSE99671 showed that MLYCD was lowly expressed in osteosarcoma tissues." (PMID 37976137, 2023). "Finally, we identified an osteosarcoma biomarker, malonyl-CoA decarboxylase (MLYCD), which showed downregulation." (PMID 37976137, 2023). "Malonyl-CoA decarboxylase (MLYCD) was downregulated in osteosarcoma cells compared to osteoblasts and may serve as a promising biomarker." (PMID 37976137, 2023). "Therefore, we investigated whether MLYCD was downregulated in osteosarcoma cells and found that overexpression of MLYCD significantly suppressed osteosarcoma cell proliferation, migration, and invasion." (PMID 37976137, 2023).
periodontitis (1 paper, 2024). An acute or chronic inflammatory process that affects the tissues that surround and support the teeth. "The results of the present study revealed a causal association between periodontitis and medium-chain specific acyl-CoA dehydrogenase (MCAD), malonyl-CoA decarboxylase (MLYCD), glutaredoxin 2 (Grx2), oligoribonuclease (ORN), and pyruvate carboxylase (PC)." (PMID 39063197, 2024). "In the present study, we demonstrated that there was a causal relationship between mitochondrial biological function and periodontitis, and discerned that MCAD, MLYCD, Grx2, ORN, and PC are significantly associated with periodontitis." (PMID 39063197, 2024).
prediabetes (1 paper, 2022). "We found two susceptibility loci in MRPS6/SLC5A3 genes associated with 2hPG, six loci in LINC01648, MATN1, CRAT37, and SLCO3A1 genes associated with HbA1C, and five loci in TRPM3/TMEM2 and MLYCD/OSGIN1 correlated to BMI in Hainan prediabetes." (PMID 35299963, 2022).
psychosis (1 paper, 2024). "According to the PICRUSt2 analysis, we observed a significant decrease in the abundance of malonyl-CoA decarboxylase (EC 4.1.1.9) in patients with schizophrenia and early-onset psychosis, which was also reflected in the reduced expression of the K01578 gene." (PMID 39458380, 2024).
renal clear cell carcinoma (1 paper, 2025). "The key regulatory factor of fatty acid synthesis metabolism, malonyl CoA decarboxylase (MLYCD), is significantly downregulated in renal clear cell carcinoma, and low expression is associated with poor prognosis in patients." (PMID 41281744, 2025).
urinary tract tumors (1 paper, 2025). "For example, in lipid metabolism, studies have shown that MLYCD, FASN, ACSM, and ACSL play important roles in the progression of urinary tract tumors." (PMID 41281744, 2025).
cancer (3 papers, 2014 to 2021). A tumor composed of atypical neoplastic, often pleomorphic cells that invade other tissues. "MLYCD is an important enzyme of fatty acid metabolism, which role in cancer therapy has been recently suggested." (PMID 25415239, 2014).
MLYCD also shares sentences with these, for which no sentence is quoted: tumor (2 papers); alcoholic liver diseases (1); aortic valve disease (1); central precocious puberty (1); developmental delay (1); geographic atrophy (1); Hypertension (1); Hypoglycemia (1); metabolic disease (1); metabolic syndrome (1); myocardial infarction (1); organic acidemia (1); schizophrenia (1).